SPRY4 (sprouty RTK signaling antagonist 4)
Description:
Suppresses the insulin receptor and EGFR-transduced MAPK signaling pathway, but does not inhibit MAPK activation by a constitutively active mutant Ras. Probably impairs the formation of GTP-Ras. Inhibits Ras-independent, but not Ras-dependent, activation of RAF1. Represses integrin-mediated cell spreading via inhibition of TESK1-mediated phosphorylation of cofilin.
Synonyms: HH17
Tractability: Antibody: UniProt places it where antibodies can reach, with high confidence; its Gene Ontology location is reachable by antibodies, with medium confidence. PROTAC: ubiquitination databases record sites on it.
Gene: Protein-coding gene on chromosome 5 (142,310,420 to 142,326,455, reverse strand). Ensembl gene ENSG00000187678.
Subcellular location: Cytoplasm; Cell projection, ruffle membrane
Subcellular location (Human Protein Atlas): Golgi apparatus; Cytosol
Gene Ontology:
Molecular function: protein binding; protein kinase inhibitor activity
Biological process: negative regulation of substrate adhesion-dependent cell spreading; negative regulation of epidermal growth factor receptor signaling pathway; negative regulation of ERK1 and ERK2 cascade; negative regulation of fibroblast growth factor receptor signaling pathway; negative regulation of Ras protein signal transduction; regulation of signal transduction
Cellular component: cytoplasm; cytosol; focal adhesion; membrane; ruffle membrane
Genetic constraint (gnomAD): Loss-of-function variants: 7 observed, 18.16 expected, observed/expected ratio (o/e) 0.39, 90% interval 0.22 to 0.72. The upper end of that interval is the gene's LOEUF score, 0.72, which puts it in group 2 of 6, group 1 being the genes least tolerant of losing a copy. Missense variants: 435 observed, 433.79 expected, observed/expected ratio (o/e) 1, 90% interval 0.93 to 1.09. Synonymous variants: 183 observed, 181.37 expected, observed/expected ratio (o/e) 1.01, 90% interval 0.89 to 1.14.
Homologues: Orthologues: chimpanzee SPRY4 (98% identical), macaque SPRY4 (98% identical), guinea pig SPRY4 (94% identical), pig SPRY4 (94% identical), rat Spry4 (93% identical), dog SPRY4 (93% identical), mouse Spry4 (93% identical), rabbit SPRY4 (93% identical), tropical clawed frog spry4 (75% identical), zebrafish spry4 (63% identical), Drosophila melanogaster sty (32% identical). Paralogues in human: SPRY1 (45% identical), SPRY2 (42% identical), SPRY3 (39% identical).
Diseases named in the same sentence as SPRY4 in open-access papers:
SPRY4 is named in the same sentence as 80 diseases in open-access papers, as found by Europe PMC text mining. Sharing a sentence is not in itself a finding about the gene and the disease. The quoted sentences say what the papers report.
breast carcinoma (18 papers, 2011 to 2025). "Protein sprouty homolog 4 (SPRY4) has been identified as another target for miR-181, the downregulation of which is associated with the progression and poor prognosis of breast cancer." (PMID 36232799, 2022). "In some breast cancer cells, decreased expression of SPRY4 appears to be associated with the invasiveness and progression of cancer, while in other cases, the function of SPRY4 may be related to the inhibition of tumor growth and metastasis." (PMID 38686189, 2024). "If the presence of the original unaltered version of Spry4 in these mesenchymal-derived cell types has had a barely perceptible effect, it is an effective inhibitor of cell proliferation and migration in breast cancer and glioblastoma-derived cells." (PMID 40806483, 2025). "A tumour-suppressive function of Spry4 was additionally shown in lung cancer and in breast cancer-derived cells." (PMID 40806483, 2025). "Compared to normal human mammary epithelial cells (nHMEC), SPRY4 protein and mRNA expression were reduced in other breast cancer cell lines (BT20, MCF7, SKBR3, MDA-MB468, ZR-75), except for the MDA-MB231 cell line." (PMID 38686189, 2024). "In contrast, inhibiting SPRY4 increased the protein level of β3-integrin, which promotes cell migration and invasion in vitro and lung metastasis in vivo in breast cancer cells." (PMID 38686189, 2024). "In response to FCS, Spry4 was inhibiting MAPK activation in breast cancer cells, while it was inefficient in osteosarcoma-derived cells." (PMID 33670044, 2021). "An oncogenic role for microRNA-181 was also reported in breast cancer, in part by targeting the 3’ untranslated region of SPRY4." (PMID 34048471, 2021). "The molecular mechanisms underlying miR-181-mediated effect in malignant progression of breast cancer have been elucidated and associated with a novel target, the tumor suppressor SPRY4 (Protein sprouty homolog 4)." (PMID 32197476, 2020). "For example, SPRY4 affects cell growth as a downstream effector of Wnt7A/Fzd9 signaling in ovarian cancer, breast cancer, colorectal cancer and prostate cancer." (PMID 32581828, 2020). "Sprouty (Spry) family genes Spry1, Spry2 and Spry4 are differentially expressed in breast cancer, but Spry3 is rarely expressed." (PMID 31671542, 2019). "In melanoma, breast cancer, and prostate cancer, SPRY4 inhibits cell migration and the cancer stem cell properties of breast carcinoma cells." (PMID 30390072, 2019). "In contrast to our findings, suppressing SPRY4 in human breast carcinoma cells resulted in a substantial increase in phosphorylation of Akt and a mild increase in phosphorylation of ERK1/228." (PMID 29410498, 2018). "The purpose of this research was to test the novel idea that Spry4 regulates cancer stem cell properties in breast cancer." (PMID 26973433, 2016). "Spry4 displays tumor suppressor activity by inhibiting tumor cell migration and proliferation in human cancers including lung, prostate and breast cancers." (PMID 26973433, 2016). "Sprouty family genes were differentially expressed across the five intrinsic breast cancer subtypes, with high expression of Spry 1 and Spry2 in normal-like cancers and higher expression of Spry4 in basal-like and normal-like cancers." (PMID 21909357, 2011). "MiR-181d plays an oncogenic role in breast cancer by repressing SPRY4." (PMID 32581828, 2020). "Similarly, in lung and breast cancer, a repression of Spry4 is coinciding with a postulated tumor-suppressive function." (PMID 31374860, 2019). "Thus, our results for the first time demonstrate a role of Spry4 in modulating CSC phenotype in the MDA-MB-231 breast cancer cell model." (PMID 26973433, 2016). "This study tests the novel idea that Spry4 regulates properties of the CSC in breast carcinoma." (PMID 26973433, 2016).
breast carcinoma (continued). "Our findings provide novel evidence that endogenous Spry4 may have tumor suppressive activity in breast cancer by suppressing cancer stem cell properties in addition to negative effects on tumor cell proliferation and migration." (PMID 26973433, 2016). "MDA-MB-231 is a human breast cancer cell line that endogenously produces Spry4 protein." (PMID 26973433, 2016). "Therefore, SPRY4 may have different biological significance and potential therapeutic target value in different subtypes and stages of breast cancer." (PMID 38686189, 2024). "This study developed a signature featuring 8 OARGs (HLA-B, RBBP8, SPRY4, WT1, WWOX, UPRT, PELO, ZNF208) and determined its prognostic and functional implications in breast cancer patients." (PMID 36960071, 2023). "In MDA-MB-231 breast cancer cells, which represent a more aggressive form of breast cancer, the PPP1R15A and SPRY4 (Sprouty4) genes are marked by a broad epigenetic (H3K4me3) domain." (PMID 34238359, 2021). "Since suppression of Spry4 enhances the CSC phenotype, we tested cell sensitivity to Paclitaxel, a common therapy for breast cancer treatment." (PMID 26973433, 2016). "In fact, we performed a similar Spry4 knockdown analysis in HTB-126, another breast cancer cell line, and found a similar increase of CSC properties in those cells." (PMID 26973433, 2016). "Reduction of SPRY4 expression, for example, increases cancer stem cell properties in MDA-MB-231 cells, while reduced expression of FOXA1 and GATA3 by inhibiting the mitogen-and stress-activated protein kinase (MSK1) enhances the metastatic progression of ER + breast cancer." (PMID 34238359, 2021). "Highlighting these genes differentially marked with the broad H3K4me3 domain in MDA-MB-231 cells (SPRY4) and in MCF7 cells (FOXA1 or GATA3) demonstrates the importance of these genes in maintaining the cellular properties of these two different types of breast cancer cells." (PMID 34238359, 2021).
ovarian carcinoma (14 papers, 2014 to 2024). A malignant neoplasm originating from the surface ovarian epithelium. "Future studies will be needed to investigate the molecular mechanisms underlying the different roles of SPRY2 and SPRY4 in the regulation of EGFR-mediated cellular function in human ovarian cancer." (PMID 27835572, 2016). "Hua KT discovered that the histone methyltransferase G9a inhibits the expression of the tumor suppressor gene SPRY4, thereby promoting the proliferation and metastasis of ovarian cancer cells." (PMID 38686189, 2024). "In breast and prostate cancers, SPRY4 can inhibit cell proliferation and migration, while in ovarian cancer, SPRY4 promotes ovarian cancer invasion." (PMID 37426199, 2023). "We evaluated possible associations between the expression of PHLDA1, SPRY4, EPHA2, and DUSP4 and MEK/ERK pathway activity in 20 ovarian cancer cell lines." (PMID 36362153, 2022). "Nevertheless, SPRY4 acts as an oncogene to promote ovarian cancer invasion and accelerate human ovarian cancer progression." (PMID 33879635, 2021). "SPRY4 is activated by a target downstream of Wnt7A/Fzd9 signaling, PPARγ, which has vital roles in ovarian cancer, colorectal cancer, and prostate cancer, and affects cell growth, differentiation, and metastasis." (PMID 30390072, 2019). "Nevertheless, as an oncogene, SPRY4 promotes ovarian cancer invasion through involvement in EGFR-mediated human ovarian cancer progression." (PMID 30390072, 2019). "In lung cancer, SPRY4 is a promising target to interdict the progress of NSCLC therapy engaged in the progression of EGFR-mediated ovarian cancer and enhances melanoma cell motility and treatment of gastrointestinal tumors." (PMID 30390072, 2019). "This is in accordance with a study in human ovarian cancer cells where suppression of SPRY4 attenuated growth factor-induced cell migration and invasion." (PMID 29410498, 2018). "In lung and prostate cancer, SPRY4 showed tumour suppressor activity, whereas in ovarian cancer, knockdown of SPRY4 attenuated growth factor-induced cancer progression." (PMID 29410498, 2018). "In ovarian cancer, SPRY4 expression levels are also down-regulated, while the changes in SPRY1 expression remain controversial." (PMID 27835572, 2016). "So what is the function and regulatory mechanism of SPRY4 in human ovarian cancer?" (PMID 38686189, 2024). "However, in other cancers, namely, testicular germ cell tumors and ovary cancers, SPRY4 was suggested to behave as an oncogene." (PMID 37686663, 2023). "In a human ovarian cancer cell line, Spry4 overexpression enhanced Areg-induced cell invasion." (PMID 29720595, 2018). "Our recent study demonstrates that SPRY4 expression is involved in the AREG-induced down-regulation of E-cadherin and invasion of human ovarian cancer cells." (PMID 27835572, 2016). "G9a depletion restored a cohort of tumor suppressor genes including E-cadherin, DUSP5, SPRY4, and PPP1R15A in ovarian cancer." (PMID 27531902, 2016). "Nonetheless, in contrast to Spry2, Spry4 fails to interfere with the malignant phenotypes of osteosarcoma and ovarian cancer." (PMID 33670044, 2021). "Although SPRY4 down-regulation is detected in ovarian cancer, the expression levels of SPRY4 do not significantly correlate with overall survival or disease-free survival." (PMID 27835572, 2016). "Importantly, microarray and quantitative RT-PCR analysis revealed that G9a regulates a cohort of tumor suppressor genes including CDH1, DUSP5, SPRY4, and PPP1R15A in ovarian cancer." (PMID 25115793, 2014). "Additionally, in osteosarcoma and in ovarian cancer, a tumor-suppressing role for Spry2 but not Spry4 was explicitly highlighted." (PMID 31374860, 2019).
melanoma (13 papers, 2015 to 2023). A malignant, usually aggressive tumor composed of atypical, neoplastic melanocytes. "As also observed in metastatic melanoma, high levels of SPRY4 are associated with prolonged survival of melanoma patients." (PMID 36076910, 2022). "MT1-MMP catalytic activity decreases the expression of the tumor suppressor SPRY4 in metastatic melanoma through an MMP-2/RAC1 pathway; a higher expression of SPRY4 correlated with a longer survival of melanoma patients." (PMID 31137480, 2019). "Our current and published data demonstrate opposite roles of MT1-MMP and SPRY4 in melanoma progression." (PMID 26392417, 2015). "We found that inhibition of SPRY4 increased melanoma cell migration, as indicated by the increase in cell distance." (PMID 26392417, 2015). "Mechanistically, we find that MT1-MMP downregulates SPRY4 expression trough an MMP2/RAC1 axis we previously showed promotes melanoma cell motility downstream of MT1-MMP." (PMID 26392417, 2015). "A publicly available data set indicated a significant decrease of SPRY4 expression in metastatic samples versus primary melanoma (Riker)." (PMID 26392417, 2015). "Our results show that SPRY4 acts as a tumor suppressor in melanoma development, as its expression is inhibited in metastatic melanoma versus primary melanoma." (PMID 26392417, 2015). "In our study, we provide the first evidence that the tumor suppressor SPRY4 is a downstream target of MT1-MMP in melanoma." (PMID 26392417, 2015). "In the present study, we show that SPRY4 expression is significantly down regulated in a majority of melanoma tumor samples and cell lines." (PMID 26392417, 2015). "By comparing these scores with the patient survival data, we found that a higher expression level of SPRY4 was correlated with longer survival of melanoma patients." (PMID 26392417, 2015). "Taken together, these data suggest that MT1-MMP promotes melanoma metastasis in part by inhibiting the tumor suppressor SPRY4." (PMID 26392417, 2015). "This study thus defined SPRY4 as a potential mediator of synthetic suppression, which is likely to contribute to the observed exclusivity between BRAF(V600E) and NRAS(Q61R) mutations in melanoma." (PMID 30651601, 2019). "Furthermore, high levels of SPRY4 expression predict better outcome and survival in melanoma patients." (PMID 26392417, 2015). "Given that MT1-MMP negatively regulates SPRY4 expression, we next wanted to determine whether one of the mechanisms of melanoma metastasis could be the inhibition of tumor suppressors such as SPRY4 by MT1-MMP." (PMID 26392417, 2015). "Finally, we demonstrate that inhibition of SPRY4 is sufficient to increase melanoma cell migration and is able to rescue cell motility that is impaired by the downregulation of MT1-MMP." (PMID 26392417, 2015). "Hence, to further assess the clinical relevance of SPRY4 in melanoma, we analyzed a melanoma tissue microarray." (PMID 26392417, 2015). "In addition, we found that higher levels of SPRY4 correlate with better prognosis and longer survival of melanoma patients." (PMID 26392417, 2015). "Further leverage of the SPRY4 pathway may also hold therapeutic promise for NRAS(Q61) melanomas." (PMID 30651601, 2019). "We therefore sought to determine whether SPRY4 was involved in melanoma cell migration." (PMID 26392417, 2015). "We found that AATBC, AC026689.1, AC083799.1, AC091544.6, LINC01287, SPRY4.AS1, and NF667.AS1 were biomarkers for genomic instability of melanoma." (PMID 34122546, 2021). "SPRY4 expression inversely correlates with that of MT1-MMP in melanoma samples and importantly, correlates with melanoma patient survival." (PMID 26392417, 2015). "Mechanistically, we show that SPRY4 is negatively regulated by MT1-MMP via an MMP2/RAC1 pathway, and importantly, negatively modulates MT1-MMP dependent cell migration in melanoma cells." (PMID 26392417, 2015).
melanoma (continued). "Notably regarded as a tumor suppressor in many cancers, SPRY4 is downregulated in glioblastoma, endometrial adenocarcinoma, perihilar cholangiocarcinoma (PHCC), breast carcinoma, melanoma, and also prostate, ovarian, and lung cancers." (PMID 36384366, 2023). "For example, in melanoma cells, upstream matrix metallopeptidase 2 (MMP2)/RAC1 signalling is increased, which results in negatively regulating the tumor suppressor function of SPRY4." (PMID 36384366, 2023). "By means of ROH island analyses, we identified the genes SPRY4, NDFIP1, IMPDH2, HSP90AB1, which might play an important role for further studies on equine melanoma." (PMID 30836959, 2019). "Melanoma cells have been shown to be “addicted” to MITF and thus the NRAS*-mediated downregulation of MITF could cooperate with the upregulation of SPRY4 to suppress growth." (PMID 30651601, 2019). "ROH island analyses identified several annotated genes (SPRY4, NDFIP1, HSP90AB1 and IMPDH2), which may play a role for further studies on equine melanoma." (PMID 30836959, 2019). "To further validate the inverse correlation between MT1-MMP and SPRY proteins and to determine whether they are expressed in melanoma, we measured the expression levels of SPRY1, SPRY2 and SPRY4 in thirteen metastatic melanoma tumor samples." (PMID 26392417, 2015). "Hence, we propose that MT1-MMP, in addition to promoting melanoma metastases by processing the ECM, does so also by repressing SPRY4, which act as a tumor suppressor in melanoma progression in part by inhibiting cell migration." (PMID 26392417, 2015). "In this study, we identified SPRY4 as a novel target of MT1-MMP, a melanoma metastasis driver gene." (PMID 26392417, 2015). "Furthermore, we observed a negative correlation of DUSP6 and SPRY4, two negative feedback regulators of MAPK signaling with the presence of CD8+ T-cells in pre-, but not in on-treatment BRAF-mutant melanoma patients (left)." (PMID 34535668, 2021).